DCLK1 (doublecortin like kinase 1)
Diseases named in the same sentence as DCLK1 in open-access papers (continued):
Sharing a sentence is not in itself a finding about the gene and the disease.
asthma (1 paper, 2022). "IL-8/CXCL8, thrombin, and DCLK1 expression were observed in the lung tissues of severe asthma patients and ovalbumin (OVA)-induced asthmatic mice model." (PMID 36369000, 2022). "In this study, IL-8/CXCL8, thrombin, and DCLK1 are found to be overexpressed in the lung tissues of severe asthma patient and OVA-challenged asthmatic mice model." (PMID 36369000, 2022). "Patients with severe asthma had higher DCLK1 expression in their bronchial tissues and epithelial cells than the normal subjects." (PMID 36369000, 2022). "The merge images show the colocalization of thrombin, IL-8/CXCL8 (MIP-2), and DCLK1 in the lung sections of severe asthma patients or OVA-challenged mice." (PMID 36369000, 2022). "The quantitative analysis indicates a significant increases in the mean intensity fluorescence (MFI) of thrombin by 254.1 ± 41.1%, IL-8/CXCL8 by 245.7 ± 35.0%, and DCLK1 by 212.4 ± 31.0% in severe asthma patients compared to normal." (PMID 36369000, 2022). "This study demonstrates that IL-8/CXCL8, thrombin, and DCLK1 are overexpressed in the bronchial tissues of severe asthma patients and OVA-induced asthmatic mice." (PMID 36369000, 2022). "The clinical and experimental study indicates that high level of IL-8/CXCL8, thrombin, and DCLK1 is related with asthma severity." (PMID 36369000, 2022). "IL-8/CXCL8, thrombin, and DCLK1 were overexpressed in the lung tissues of severe asthma patients and ovalbumin (OVA)-induced asthmatic mice model." (PMID 36369000, 2022). "Based on the accumulated evidence, DCLK1 overexpression in different cells plays an important pathological role in various diseases, but whether DCLK1 is involved in severe asthma remains unknown." (PMID 36369000, 2022). "Next, we examined whether the bronchial tissues of patients with severe asthma would overexpress DCLK1." (PMID 36369000, 2022). "As the therapy for severe asthma remains challenging, the finding of DCLK1 as a potential marker may be beneficial as a target therapy." (PMID 36369000, 2022). "To confirm whether thrombin, IL-8/CXCL8 (MIP-2), and DCLK1 are highly expressed in lung tissues of asthma patients and OVA-induced mice, we performed triple staining immunofluorescence." (PMID 36369000, 2022). "As IL-8/CXCL8 is a potent chemoattractant of neutrophil and airway neutrophilia is correlated with asthma severity, DCLK1 involvement in the thrombin-stimulated IL-8/CXCL8 expression pathway indicates that DCLK1 might serve as a new biological marker of severe asthma." (PMID 36369000, 2022). "However, the regulators of DCLK1 expression in lung epithelial cells in severe asthma remain unclear, and further studies are required to address these issues." (PMID 36369000, 2022). "However, the pathologic role of DCLK1 in asthma and its involvement in thrombin-stimulated IL-8/CXCL8 expression remain unknown." (PMID 36369000, 2022). "DCLK1 might be essential in thrombin-stimulated IL-8/CXCL8 expression in asthmatic lungs and indicates a potential therapeutic strategy for severe asthma treatment." (PMID 36369000, 2022).
bladder cancers (1 paper, 2025). "Moreover, DCLK1 is overexpressed in colorectal, pancreatic, hepatocellular, breast, and bladder cancers, suggesting its widespread activation during oncogenesis." (PMID 40775208, 2025).
celiac disease (1 paper, 2020). An autoimmune genetic disorder with an unknown pattern of inheritance that primarily affects the digestive tract. "Another study showed that the number of DCLK1-positive cells decreased in intestinal tissue from patients with celiac disease." (PMID 32823895, 2020).
chronic hepatitis B (1 paper, 2015). "However, it is expressed above the baseline in non-HCV cases such as NASH and in chronic hepatitis B suggesting that DCLK1 can also be induced by other factors." (PMID 25948779, 2015).
Chronic Obstructive Asthma (1 paper, 2022). Chronic airway obstruction caused by asthma. "As previous findings showed that fibrocytes, fibroblasts, and smooth muscle cells contributes in the pathogenesis airway fibrosis in chronic obstructive asthma patients, further studies to explore the involvement of DCLK1 in those cells also need to be performed." (PMID 36369000, 2022).
chronic rhinosinusitis (1 paper, 2024). Chronic form of sinusitis. "Aeroallergens induce DCLK1+IL-25+ tracheal tuft cell expansion in mice and DCLK1+ tuft cells produce IL-25 in patients with chronic rhinosinusitis with nasal polyps." (PMID 38061015, 2024).
co-infection (1 paper, 2024). "Consistent with published data, infection with H. bakeri resulted in DCLK1+ tuft cell hyperplasia, but the tuft cell hyperplasia was not affected by co-infection with H. diminuta." (PMID 39083533, 2024).
cognitive deficits (1 paper, 2012). "SCZ and ADHD are both characterised by severe cognitive deficits, mostly in attention and general cognition, and they both manifest early in development, which is in accordance with an effect of DCLK1 on neurodevelopment and cognitive phenotypes." (PMID 22539971, 2012).
colon adenoma (1 paper, 2022). An adenoma that arises from the colon. "We used a second inflammation-induced colon adenoma model in which Apc truncation is driven by Cre-mediated recombination of the Apc allele (Apcfl/fl) in Dclk1+ cells." (PMID 36860494, 2022). "Apcmin/+ and doublecortin-like kinase 1 (Dclk1)Cre/+;Apcfl/fl mice were exposed to dextran sulphate sodium (DSS) in their drinking water to promote the formation of colon adenomas." (PMID 36860494, 2022).
colorectal tumors (1 paper, 2021). "According to previous evidence, raised levels of Doublecortin-like kinase 1 (DCLK1) expression in human colorectal tumors are associated with higher mortality rates." (PMID 33494834, 2021).
diabetic cardiomyopathy (1 paper, 2025). Diabetic cardiomyopathy is a disorder of the heart muscle in people with diabetes. "An additional study has provided evidence that reducing Dclk1 in the context of diabetic cardiomyopathy through genetic knockout or inhibitors can reduce cardiac fibrosis." (PMID 40332511, 2025).
diabetic nephropathy (1 paper, 2024). "DCLK1 expression increases in individuals with diabetic nephropathy." (PMID 39845838, 2024). "The specific role DCLK1 plays in diabetic nephropathy and neuropathy has not been thoroughly investigated." (PMID 39845838, 2024).
dysplasia (1 paper, 2014). A usually neoplastic transformation of the cell, associated with altered architectural tissue patterns. "To demonstrate the functional significance of Dclk1 in intestinal tumorigenesis, we conducted Dclk1 knockdown experiments with siDCLK1-NPs and found decreased dysplasia/adenocarcinoma, and fewer polyps in ApcMin/+ mice." (PMID 25211188, 2014).
epilepsy (1 paper, 2019). A brain disorder characterized by episodes of abnormally increased neuronal discharge resulting in transient episodes of sensory or motor neurological dysfunction, or psychic dysfunction. "By real-time PCR, we detected a down-regulation of Arx, Cdkl5, and Dclk1 genes, human homologues of which are involved in etiology of epilepsy." (PMID 31698854, 2019).
gastric adenoma (1 paper, 2023). A neoplastic polyp that arises from the stomach. "We therefore explored whether tuft cells contributed to gastric adenoma formation by generating gp130;F/FBAC(Dclk1::CreERT2);Rosa26DTA/+ (gp130;F/FTCΔ) compound mutant mice to enable inducible tuft cell ablation in response to LDTmx." (PMID 37898600, 2023).
hearing loss (1 paper, 2020). "We analysed a total of 17 genes and found one, Dclk1, that was associated with late-onset hearing loss and one, A430005L14Rik, that affected auditory function following noise-induced damage." (PMID 31927188, 2020). "•Dclk1 may play a role in progressive age-related hearing loss." (PMID 31927188, 2020).
hyperplastic polyp (1 paper, 2017). A polyp found mainly in the stomach and colon. "Although the number of DCLK1+ cells slightly increased in hyperplastic polyps, the staining pattern was similar to normal colon tissue." (PMID 29254234, 2017). "Finally, compared to normal colon biopsies and hyperplastic polyps, DCLK1 expression increased in human tubular adenomas and invasive colorectal cancers." (PMID 29254234, 2017).
intestinal neuroendocrine tumors (1 paper, 2015). "The present study conducted immunohistochemical analyses for DCLK1 and the stemness marker, NANOG, in human intestinal neuroendocrine tumors (NETs), as their expression had not been previously investigated in these tumors." (PMID 26622789, 2015).
leukemia (1 paper, 2023). A malignant (clonal) hematologic disorder, involving hematopoietic stem cells and characterized by the presence of primitive or atypical myeloid or lymphoid cells in the bone marrow and the blood. "Furthermore, expression of the Tuft cell marker DCLK-1 (double cortin-like kinase-1) and IL-25, which is secreted by Tuft cells and regulates type 2 immune responses, increased in a time-dependent manner that coincided with the temporal kinetics of leukemia progression." (PMID 38042840, 2023).
Lissencephaly (1 paper, 2021). A spectrum of malformations of cortical development caused by insufficient neuronal migration that subsumes the terms agyria, pachygyria and subcortical band heterotopia. "DCLK1 was originally identified as a causative gene of cerebral cortical malformation such as lissencephaly and was later found to regulate neuronal migration and axon outgrowth." (PMID 34573300, 2021).
lung adenocarcinoma (1 paper, 2023). A carcinoma that arises from the lung and is characterized by the presence of malignant glandular epithelial cells. "We, therefore, aimed to explore the role of doublecortin-like kinase 1 (DCLK1) as an EMT driver gene in the acquired resistance of lung adenocarcinoma to EGFR-TKIs." (PMID 37239162, 2023). "Additionally, the transwell assay also confirmed that DCLK1 rescue enhances the migration and invasion abilities of lung adenocarcinoma cells." (PMID 37239162, 2023). "In conclusion, our results indicate the role of DCLK1 in the development of EGFR-TKI resistance in lung adenocarcinoma that has undergone EMT, and targeting DCLK1 could be used as a new option for posterior-line treatment of EGFR-TKI-acquired resistance tumor." (PMID 37239162, 2023). "In addition, our previous study confirmed that the increased expression of DCLK1 in lung adenocarcinoma contributes to EGFR-TKI-acquired resistance, partly due to the maintenance of tumor cell stemness." (PMID 37239162, 2023). "In addition, DCLK1 expression was markedly increased in EGFR-TKI-resistant lung adenocarcinoma cells." (PMID 37239162, 2023). "In contrast, inhibition of DCLK1 reversed the occurrence of EMT and reduced the resistance of lung adenocarcinoma cells to EGFR-TKI." (PMID 37239162, 2023). "In addition, similar results were obtained from the immunofluorescence assay, confirming the involvement of DCLK1 in remodeling the EMT process and influencing the sensitivity of lung adenocarcinoma cells to EGFR-TKI." (PMID 37239162, 2023). "In this study, the biological function of DCLK1 in EGFR-TKI-resistant lung adenocarcinoma via remodeling the EMT process was explored through in vitro and in vivo experiments, with the aim of finding potential therapeutic targets in EGFR-TKI-resistant lung adenocarcinoma." (PMID 37239162, 2023).
lymph node metastasis (1 paper, 2022). "The relationship between DCLK1 expression and lymph node metastasis was evaluated in five studies including 461 patients." (PMID 35717205, 2022).
metastasis (1 paper, 2017). The spread or migration of cancer cells from one part of the body (where they first appeared) to another. "Fourteen studies investigated the expressions of DCLK1 in different status of lymphatic metastasis, including 1172 cases of positive lymphatic metastasis and 1199 cases of negative lymphatic metastasis." (PMID 29246000, 2017).
myelofibrosis (1 paper, 2021). A partial or complete replacement of the bone marrow stroma by fibrous tissue. "Then, we report a complex structure of DCLK1 kinase domain with the most potent inhibitor ruxolitinib, which has been originally developed as a Janus kinases (JAK1 and JAK2) inhibitor for treatment of myelofibrosis." (PMID 34445192, 2021).
nasopharyngeal carcinoma (1 paper, 2025). A carcinoma arising from the nasopharyngeal epithelium. "Moreover, research has suggested that miR-223-5p suppresses the progression of nasopharyngeal carcinoma by targeting DCLK1." (PMID 39854306, 2025).
oropharyngeal cancers (1 paper, 2021). Carcinoma, predominantly squamous cell, arising from the epithelial cells of the oropharynx. "Although it was reported that DCLK1 is associated with poor prognosis in oropharyngeal cancers, very little is known about the molecular characterization of DCLK1 in HNSCC." (PMID 34336664, 2021).
osteoarthritis (1 paper, 2026). A noninflammatory degenerative joint disease occurring chiefly in older persons, characterized by degeneration of the articular cartilage, hypertrophy of bone at the margins and changes in the synovial membrane. "Genetic and pharmacological translational evidence validates the p-STAT3/DCLK1 axis as a prospective therapeutic target against osteoarthritis." (PMID 42298903, 2026). "A novel p-STAT3/DCLK1/IKKβ/NF-κB axis regulates chondrocyte extracellular matrix (ECM) metabolism and drives osteoarthritis progression." (PMID 42298903, 2026).
parasitic infection (1 paper, 2021). "In response to CR infection, there was an expansion of the DCLK1+ cells reminiscent of tuft cell hyperplasia seen in the small intestine in response to parasitic infection." (PMID 34226497, 2021).
polyp (1 paper, 2022). A usually exophytic mass attached to the underlying tissue by a broad base or a thin stalk. "Healthy human sinus tuft cells resembled previous descriptions of human airway tuft cells, while canonical markers of mouse tuft cells such as TRPM5 and DCLK1 were present only in the allergic tuft cell population in polyp patients." (PMID 35608904, 2022).
rectal NET (1 paper, 2015). "In conclusion, DCLK1 may be a novel marker for rectal NET, potentially indicating the presence of the stemness gene product, NANOG." (PMID 26622789, 2015). "In the present study, the strong expression of DCLK1 in rectal NETs was demonstrated." (PMID 26622789, 2015).
Stroke (1 paper, 2013). Sudden impairment of blood flow to a part of the brain due to occlusion or rupture of an artery to the brain. "AF030089 and MRAK135044 are stroke-induced lncRNAs that originate from a sense exon and sense intron, respectively, of the Dclk1 gene." (PMID 24063527, 2013). "Some Sin3A-enriched lncRNAs transcribed from intragenic loci that are particularly relevant to stroke, such as the transcription factor Fos, Dclk1 and the astrocytic activation marker GFAP." (PMID 24063527, 2013). "Interestingly, the Dclk1 locus produced two lncRNAs, both of which were significantly induced after stroke and showed increased binding to Sin3A compared with sham." (PMID 24063527, 2013).
tubular adenoma (1 paper, 2017). A usually polypoid neoplasm arising from the glandular epithelium. "In contrast, staining for DCLK1 in biopsies of tubular adenomas and invasive cancers was significantly increased compared to staining of normal and hyperplastic tissue." (PMID 29254234, 2017).
ulcerative colitis (1 paper, 2021). An inflammatory bowel disease involving the mucosal surface of the large intestine and rectum. "In the FFPE (formalin-fixed paraffin-embedded) sections prepared from the colons of ulcerative colitis (UC) and immune-mediated colitis (IRAEC) patients, expression of DCLK1 isoforms correlated positively with Notch1 and negatively with a transcriptional repressor, FoxD3 (Forkhead Box D3)." (PMID 34226497, 2021).
cancer (158 papers, 2011 to 2026). A tumor composed of atypical neoplastic, often pleomorphic cells that invade other tissues. "Upregulated DCLK1 has been used to identify patients at high risk of cancer progression and tumours with chemotherapy-resistance." (PMID 38062554, 2024). "Doublecortin-like kinase 1 (DCLK) is a microtubule-associated serine/threonine kinase that is upregulated in a wide range of cancers and is believed to be related to tumour growth and development." (PMID 38062554, 2024). "Doublecortin-like kinase 1 (DCLK1) is a prominent kinase involved in carcinogenesis, serving as a diagnostic marker for early cancer detection and prevention, as well as a target for cancer therapy." (PMID 37762326, 2023). "In our previous study, several somatic DCLK1 cancer mutations in the AID and its binding regions in the kinase domain were found from the COSMIC (Catalogue of Somatic Mutations in Cancer) database." (PMID 37762326, 2023). "According to the National Cancer Institutes’ genomic data commons portal, the DCLK1 gene is mutated in 394 out of 13,582 cases across 31 projects which include over 20 different cancer types and primary sites." (PMID 36979969, 2023). "Numerous studies have implicated the high expression of DCLK1 with poor prognosis and that the inhibition of DCLK1 via a variety of methods suggests that targeting DCLK1 is a viable strategy for cancer therapy." (PMID 38003596, 2023). "Cancer-associated tuft cells in the mouse prostate express DCLK1, COX1, COX2, while human tuft cells express COX1." (PMID 37386128, 2023). "Doublecortin‐like kinase 1 (DCLK1), a microtubule‐associated protein kinase, is involved in neurogenesis and human cancers." (PMID 36896602, 2023). "DCLK1 is a proposed cancer driver gene, and its upregulation is associated with poor overall survival in several solid cancer types." (PMID 36979969, 2023). "By analyzing this structure, we were able to uncover the intricate molecular mechanisms behind specific cancer-causing mutations in DCLK1." (PMID 37762326, 2023). "Our research provided a valuable understanding of the cancers caused by DCLK1 mutations and a new way for the development of the drugs targeting it." (PMID 37762326, 2023). "An example of this is the gene doublecortin-like kinase-1 (DCLK1), a well-recognized marker for CSCs that is linked with aggressive cancer types and resistance to treatment." (PMID 38003596, 2023). "Collectively, these findings underlined that DCLK1 promoted cancer stemness and 5‐fluorouracil resistance in CRC." (PMID 35522902, 2022). "DCLK1 has been shown to promote EMT and associate with poor prognosis in several cancers, suggesting DCLK1 is a potential therapeutic target for cancer invasion and metastasis." (PMID 36210463, 2022). "Analysis of 233 primary and 40 recurrent HNSCC cancer biopsies revealed that high DCLK1 expression was associated with poor prognosis and showed a trend towards higher active NOTCH1 expression in tumors with elevated DCLK1." (PMID 34336664, 2021). "DCLK1-expressing CSCs regulate multiple biological processes in cancer, promote resistance to therapy, and are associated with metastasis." (PMID 33348546, 2020). "Recent studies suggest that DCLK1, a newly identified cancer stem cell marker, can mark gastrointestinal cancer stem cells and is closely associated with cancer metastasis and angiogenesis in many cancers." (PMID 31223610, 2019). "In this meta-analysis including 18 retrospective studies with a total of 2660 patients, we clarified the association between expression of DCLK1 and the clinicopathological characteristics of malignant tumors." (PMID 29246000, 2017). "Significant association existed between DCLK1 level and cancer tissues, indicating that expression of DCLK1 was dramatically higher in cancer tissues than that in normal tissues." (PMID 29246000, 2017).